ERBB2 (erb-b2 receptor tyrosine kinase 2)
Diseases named in the same sentence as ERBB2 in open-access papers (continued):
Sharing a sentence is not in itself a finding about the gene and the disease.
breast cancer (continued). "A central intracellular signaling pathway activated by ErbB2 is the PI3K/Akt pathway, whose importance in breast cancer is corroborated by clinical studies showing Akt activation in most ErbB2-overexpressing tumors." (PMID 20649976, 2010). "The ERBB2 overexpressing ductal breast carcinomas were analyzed with respect to size, tumor stage and histological grade, presence or absence of axillary lymph node metastasis, and nuclear KLF6 immunostain." (PMID 20126619, 2010). "Around 20% of breast cancers (BC) show ERBB2 gene amplification and overexpression of the ERBB2 tyrosine kinase receptor." (PMID 20932292, 2010). "Addition of doxycycline to the culture medium resulted in overexpression of oncogenic ERBB2 to levels seen in overexpressing breast carcinomas." (PMID 20584310, 2010). "EphA2 formed a complex with ErbB2 in both human and murine breast carcinoma cells, leading to enhanced signaling through Ras-MAPK activation and ultimately promoting tumor progression." (PMID 20064265, 2010). "It has been shown that decorin functionally inactivates the ErbB2 protein in breast carcinoma cells, leading to growth suppression and cytodifferentiation of mammary carcinoma cells." (PMID 20092659, 2010). "Ku proteins in interaction with AP-2 (α and γ) contribute to increased ERBB2 mRNA and protein levels in breast cancer cells." (PMID 19906305, 2009). "In this sense, those with ERBB2+ tumors metastasized less often to bone than ERBB2- breast cancers, which was relatively consistent with Kallioniemi's findings." (PMID 19778431, 2009). "In summary, the present study contributes to a better understanding of the regulation of ERBB2 gene expression in breast cancer cells, by demonstrating the implication of Ku proteins together with AP-2 transcription factors in the expression of the oncogene." (PMID 19906305, 2009). "Amplification and overexpression of HER-2/neu (c-erbB-2) predict an especially poor prognosis in breast cancer." (PMID 19128465, 2009). "Truncated versions of ERBB2 have been shown to actively participate in signalling and to be resistant to trastuzumab treatment in breast cancer." (PMID 19183447, 2009). "The most common regions of high-level amplification in breast cancer are 17q12 (targeting ERBB2), 11q13 (CCND1), 8q24 (MYC); 8p11-p12; 17q22-25; and 20q13." (PMID 19995430, 2009). "The involvement of AP-2α and AP-2γ factors in ERBB2 overexpression has been described in several breast cancer cell lines." (PMID 19906305, 2009). "Breast cancer patients that are both ERα-positive and ErbB2-positive are resistant to tamoxifen therapy." (PMID 19383165, 2009). "PPARγ activity is necessary for the viability specifically of ERBB2-positive breast cancer cells, in a similar manner to PBP and NR1D1 (Kourtidis A, unpublished data; Carkner RD, Eifert C, Brosnan MJ, Conklin DS)." (PMID 19298655, 2009). "In this context, we identified palmitate-induced lipotoxicity as a main effect of PPARγ inhibition in ERBB2-positive breast cancer cells." (PMID 19298655, 2009). "Activator protein-2 (AP-2) α and AP-2γ transcription factors contribute to ERBB2 gene overexpression in breast cancer." (PMID 19906305, 2009). "Endogenous palmitate toxicity represents a genetically based property of ERBB2-positive breast cancer that can be exploited for therapeutic intervention." (PMID 19298655, 2009). "Neu/ErbB2 is a member of the epidermal growth factor receptor family that is amplified and overexpressed in 20 to 30% of human breast cancers and correlates with poor prognosis." (PMID 19703301, 2009). "Apart from breast cancer, ERBB2 amplification has been found in other malignant tumours, such as ovarian, lung, colon, and gastric carcinomas." (PMID 19156142, 2009). "In anattempt to discover cancer relevant lysosomal motor proteins, we comparedthe lysosomal proteomes from parental MCF-7 breast cancer cells with thosefrom highly invasive MCF-7 cells that express an active form of the ErbB2(ΔN-ErbB2)." (PMID 19242560, 2009).
breast cancer (continued). "In order to investigate the biology of these specific breast cancers, we chose to study the deregulation of ERBB2 gene expression." (PMID 19906305, 2009). "Another group showed that gefitinib improved tumor oxygenation in ErbB2 expressing breast cancer xenografts using EF5 flow cytometry." (PMID 19657384, 2009). "The tight genetic linkage between PBP, NR1D1, and ERBB2 on the 17q12-21 amplicon commonly found in breast cancers suggests that ERBB2-positive breast cancer cells are genetically preprogrammed to depend on fatty acid synthesis for energy production." (PMID 19298655, 2009). "We sought to examine the reasons for the dependence of ERBB2-positive breast cancer cells on PPARγ for survival." (PMID 19298655, 2009). "When used as single-agent therapy in patients with metastatic ERBB2-positive breast cancer, response rates ranging from 11% to 26% have been observed." (PMID 19298655, 2009). "PPARγ inhibition in ERBB2-positive breast cancer cells resulted in cell death and apoptosis, similar to the effects of PBP and NR1D1 inhibition (Kourtidis A, Carkner RD, Eifert C, Brosnan MJ, Conklin DS; unpublished data)." (PMID 19298655, 2009). "hCAP18 mRNA was quantified in 109 primary breast cancers and compared with clinical findings and ERBB2 mRNA expression." (PMID 19183447, 2009). "Epidermal growth factor receptor-2 (ErbB-2/HER2) is a potent breast oncogene that has been shown to be amplified in 20% of breast cancers." (PMID 20024517, 2009). "This supports an important function of ErbB2 signalling in the regulation of FA turnover in invasive breast cancer cells." (PMID 19190626, 2009). "A recent study has indicated a synergistic interaction between an ErbB2 directed monoclonal antibody Herceptin/Trastuzumab and Velcade with respect to cell death of tissue cultured breast cancer cells." (PMID 19436748, 2009). "To relate mitogenic input to response to βGBP we examined non-invasive MCF-7 breast cancer cells, which have low levels of ErbB2, in their naïve state and when treated with cholera toxin (MCF-7CTx)." (PMID 19133120, 2009). "ERBB2-positive breast cancer cells are sensitive to inhibition of both FASN and malic enzyme 1 genes (Kourtidis A, Carkner RD, Eifert C, Brosnan MJ, Conklin DS; unpublished data)." (PMID 19298655, 2009). "Both EgfR and ErbB2 are overexpressed in a substantial fraction of breast cancers and are recognized targets for breast cancer therapy." (PMID 19317917, 2009). "In order to improve the current understanding of AP-2 (α and γ) activity, we sought here to identify further AP-2α interacting factors contributing to ERBB2 gene overexpression in breast cancer cells." (PMID 19906305, 2009). "Only 8% of basal breast cancers were ER-positive for 23.5% of ERBB2, 95.5% of luminal A, 100% of luminal B and 53.8% of normal-like breast cancers." (PMID 19405945, 2009). "Noticeable, the antiproliferative activity of Herceptin on ErbB2-positive breast cancer cells is minimal compared with its drastic anti-invasive activity." (PMID 19190626, 2009). "Our findings indicate that PPARγ activity enables ERBB2-positive breast cancer cells, which produce high levels of fat, to convert fatty acids to triglycerides, allowing these cells to avert the cell death that results from lipotoxicity." (PMID 19298655, 2009). "This alteration is present in about 20% of breast cancers and was found to be predictive of poor prognosis before the development of ERBB2 targeted drugs." (PMID 19906305, 2009). "Nevertheless, a number of reports have indicated that the Mediterranean diet, which is rich in the unsaturated oleate-containing olive oil, has anti-oncogenic properties against ERBB2-positive breast cancer." (PMID 19298655, 2009). "A clinical trial using intratumoral delivery of adenovirus E1A, which can also repress ERBB2 expression, has been launched in breast cancer." (PMID 19226453, 2009).
breast cancer (continued). "Our data strongly suggest that inhibition of Cdk2 and/or Pin1 in ERα-positive and ErbB2-positive breast cancer cells will enhance the anti-tumor activity of tamoxifen." (PMID 19383165, 2009). "The relatively high levels of activity of the fatty acid synthesis pathway in the ERBB2-positive breast cancer cells are likely to require a mechanism for overcoming the toxic effects of palmitate excess." (PMID 19298655, 2009). "Recent advances in genomic techniques have led to the classification of breast cancer into five distinct subtypes: the luminal A, luminal B, ERBB2+, normal breast-like and basal-like subtype." (PMID 19778431, 2009). "Amplification of the ERBB2 oncogene is one of the most clinically relevant genetic changes in breast cancer and occurs in 10% to 34% of breast cancer cases." (PMID 19298655, 2009). "In breast cancer, overexpression of the transmembrane tyrosine kinase ERBB2 is an adverse prognostic marker, and occurs in almost 30% of the patients." (PMID 19118495, 2009). "PPARγ enables ERBB2-positive breast cancer cells to convert fatty acids to triglycerides in order to avert lipotoxicity caused by the significantly high levels of fats that these cells produce." (PMID 19298655, 2009). "ERBB2-positive breast cancer cells are more sensitive to inhibition of PPARγ activity by the antagonist GW9662." (PMID 19298655, 2009). "For example, the non-receptor tyrosine kinase c-Src is often aberrantly expressed or activated in human breast cancers, sometimes as a consequence of dys-regulated ErbB2 activity." (PMID 19737390, 2009). "On the basis of these observations, we sought to examine if Src plays a role in Herceptin-induced regulation of FAs in ErbB2-positive breast cancer cells." (PMID 19190626, 2009). "Effects of exogenous LL-37 and transgenic overexpression of hCAP18 on ErbB2 signalling were investigated by immunoblotting using extracts from breast cancer cell lines ZR75-1 and derivatives of MCF7." (PMID 19183447, 2009). "The association of ERBB2 amplification with aggressive disease and poor clinical outcome in breast cancer has made ERBB2 an attractive therapeutic target." (PMID 19298655, 2009). "Several mouse models have been generated to examine mechanisms involved in ErbB2-mediated mammary tumor progression." (PMID 19703301, 2009). "Our results implicate Ku proteins in breast cancer by contributing to ERBB2 gene overexpression and thus the accumulation of excessive amounts of the receptor." (PMID 19906305, 2009). "And most dichotomized cases according to hormone receptor status or as triple negative/non-triple negative, which obscures the superiority of ERBB2 status to hormone receptor (HR) status as a prognosticator in breast cancer." (PMID 19778431, 2009). "In breast carcinomas, ERBB2 functions as an oncogene, as amplification of the gene induces protein overexpression in the cell membrane." (PMID 19156142, 2009). "More recently, trastuzumab was shown to be effective as adjuvant treatment in breast-carcinoma patients with ERBB2 amplification/overexpression." (PMID 19156142, 2009). "This is in particular true for ErbB2 which is over-expressed in more than 25% of all breast carcinoma." (PMID 19911055, 2009). "Next, we examined the response to trastuzumab treatment of breast carcinoma cells with high ERBB2 expression (HCC1954 and SK-BR-3) as compared to cells with low ERBB2 level (MCF-7) in a viability assay." (PMID 19118495, 2009). "MCF7 breast cancer cells stably transfected with ErbB2/Her2 displayedreduced differentiation and enhanced resistance to TZD-driven inhibition ofanchorage-independent growth." (PMID 18596912, 2008). "The functional role of AP-2α and YY1 on ERBB2 gene expression was analyzed by small interfering RNA (siRNA) transfection in the BT-474 mammary cancer cell line followed by real-time reverse transcription-polymerase chain reaction and Western blotting." (PMID 18218085, 2008).
breast cancer (continued). "The monoclonal antibody Trastuzumab is FDA-approved for the treatment of breast cancer and inhibits the homodimerization of ErbB2." (PMID 19077306, 2008). "Inhibition of the mTOR pathway is effective in inhibiting tumor growth in cell lines and in xenograft models of erbB2-overexpressing breast cancer and is currently under investigation in clinical trials." (PMID 19077306, 2008). "In fact, one of the most well-defined client proteins in breast cancer is the receptor tyrosine kinase ERBB2/Her2/EGFR2." (PMID 18430202, 2008). "In human breast cancer cells that over-express ErbB2 and have also developed resistance to tyrosine kinase inhibitor therapy, there is active PI3K/Akt via ErbB3 signaling." (PMID 19019207, 2008). "ErbB2 levels in breast cancer cells treated with Cycloheximide started to decrease within 3 to 6 hours of Cycloheximide treatment, and continued to drop after 9 hours." (PMID 19077306, 2008). "In breast cancers with amplified ERBB2, ErbB3 augments ErbB2 signaling through strong coupling to survival pathways that complement the signals emanating from ErbB2, thus allowing the cancer cells to escape from inhibition therapy." (PMID 19019207, 2008). "Mammary tumours from transgenic mice expressing activated mutants of ErbB2 also express elevated levels of total and tyrosine-phosphorylated ErbB2 and ErbB3." (PMID 18700973, 2008). "BT-474 breast cancer cells overexpressing ERBB2, both through amplification and enhanced transcription, were transfected with AP-2α and AP-2γ siRNAs, both independently and in combination for several days." (PMID 18218085, 2008). "Therapeutic blockade of ErbB2 with the monoclonal antibody trastuzumab improves the effectiveness of chemotherapy and survival in breast cancer." (PMID 18475301, 2008). "During the past decade, progress in endocrine therapy and the use of trastuzumab has significantly contributed to the decline in breast cancer mortality for hormone receptor-positive and ERBB2 (HER2)-positive cases, respectively." (PMID 19007432, 2008). "The receptor ErbB3/HER3 is often over-expressed in human breast cancers, frequently in conjunction with over-expression of the proto-oncogene ERBB2/HER2/NEU." (PMID 19019207, 2008). "Recently, Li and colleagues proposed that AP-2α overexpression in breast cancer cells is the consequence of a stabilization of the protein resulting from a defective proteasomal degradation, leading to an increased ERBB2 gene expression." (PMID 18218085, 2008). "Our siRNA results further indicate that both AP-2α and AP-2γ are required for ERBB2 overexpression, as already suggested in a study on breast cancer tissues by Turner and colleagues." (PMID 18218085, 2008). "Increased expression of GRB7 correlates with a lower survival rate in breast cancer patients with tumors with either high or low expression of ERBB2." (PMID 19424485, 2008). "Several laboratories have undertaken the study of the mechanisms leading to the accumulation of high levels of ERBB2 transcript and corresponding protein in breast cancer cells." (PMID 18218085, 2008). "Several studies have shown a link between activator protein 2 (AP-2) transcription factors and ERBB2 gene expression in breast cancer cell lines." (PMID 18218085, 2008). "Transfection of siRNAs targeting AP-2α and AP-2γ mRNAs in the BT-474 breast cancer cell line repressed the expression of the endogenous ERBB2 gene at both the mRNA and protein levels." (PMID 18218085, 2008). "The majority of the work presented in this report was performed in the BT-474 breast cancer cell line, which is driven by ERBB2 and depends on estrogen for growth." (PMID 18430202, 2008). "We first evaluated the expression level of ERα and ERβ, β4 integrin subunit, ErbB2, and ErbB-3 in a series of human mammary tumor cell lines including MDA-MB 231, MDA-MB 361, SKBr3, BT474, BT549, and T47D." (PMID 18270579, 2008).
breast cancer (continued). "In particular, expression of a dominant negative AP-2 protein in mammary cancer cells was shown to result in the inhibition of the transcription from a reporter vector bearing a 6-kb fragment of the ERBB2 promoter." (PMID 18218085, 2008). "In breast cancer driven by gene amplification and overexpression of ErbB2, disruption of ErbB2-dependent signalling with either trastuzumab or the small-molecule tyrosine kinase inhibitor lapatinib is correlated with clinical efficacy." (PMID 18841159, 2008). "Of note, basal and ERBB2 subgroups have been found to respond better to 5-fluorouarcil, doxorubicin and cyclophosphamide chemotherapy relative to other breast cancer subgroups." (PMID 18182985, 2008). "Trastuzumab is an anti-erbB2 mAb which increases response rates and improves survival in patients with erbB2-overexpressing breast cancer when combined with conventional chemotherapy." (PMID 18991714, 2008). "The ErbB3 growth factor receptor is being increasingly recognised as a central player in ErbB2-driven breast cancer." (PMID 18841159, 2008). "The tumours arising in these animals show strong similarity to human ER-negative, ErbB2-postitive breast cancer as shown in a recent paper." (PMID 18362934, 2008). "Trastuzumab prolongs the survival of patients with metastatic ERBB2 (HER2)-positive breast cancer and leads to dramatic improvements in prognosis when used in adjuvant therapy." (PMID 19007432, 2008). "We demonstrated, for the first time, the implication of AP-2α in combination with its cofactor, YY1, in ERBB2 oncogene overexpression in breast tumors both in vitro and in breast cancer tissue specimens." (PMID 18218085, 2008). "MMTV-c-ErbB2 (line 202) mice express the wild type rat ERBB2 gene in the mammary gland and have been an extensively used model of mammary carcinomas." (PMID 18700973, 2008). "Unfortunately, only a fraction of patients with ERBB2-amplified breast carcinomas respond to Trastuzumab, further evidence for heterogeneity among these tumors." (PMID 18702822, 2008). "The activity of trastuzumab in breast carcinomas overexpressing ERBB2 has contributed to the concept that certain tumours are ‘oncogene dependent’." (PMID 18454161, 2008). "Human breast carcinomas overexpress ErbB2 in 20% to 30% of cases and patients with this type of tumour bear a poor prognosis and are currently treated with trastuzumab, a humanised monoclonal antibody." (PMID 18700973, 2008). "Although the probability of remission is much better in Herceptest 3+ breast carcinomas compared with tumours with lower levels of ERBB2, still about 50% of Herceptest 3+ breast carcinomas are resistant to trastuzumab." (PMID 18454161, 2008). "It has previously been demonstrated that combined targeting of EGFR and erbB2 is more effective than targeting either agent alone in inhibiting growth of erbB2-overexpressing breast cancer cells." (PMID 17686159, 2007). "In the previous Creighton study, ER+ MCF-7 breast cancer cells were made to stably over-express EGFR or constitutively activate erbB-2, Raf, or MEK; which resulted in these cells exhibiting estrogen-independent growth and the down-regulation of ER expression." (PMID 17598908, 2007). "Breast cancer cases in both the basal-like and ERBB2+ groups had a very high mortality rate during the first two years, while the highly proliferating luminal cases developed the disease more slowly, showing highest mortality after five to eight years." (PMID 17504517, 2007). "Breast cancer cells over-expressing ErbB2 depend on its activity for proliferation, because treatment of these cells with ErbB2-specific antagonistic antibodies or kinase inhibitors blocks tumor cells in the G1 phase of the cell cycle." (PMID 19384426, 2007). "Herceptin, the only anti-ErbB2, humanised monoclonal antibody approved by FDA for therapy of mammary carcinoma is currently and successfully prescribed for treatment of ErbB2-positive breast cancer." (PMID 17923870, 2007).